TRIM29 (tripartite motif containing 29)
Diseases named in the same sentence as TRIM29 in open-access papers (continued):
Sharing a sentence is not in itself a finding about the gene and the disease.
colon cancer (4 papers, 2021 to 2024). "In the present study, we explored the specific mechanism of action of TRIM29 in colon cancer progression." (PMID 37671092, 2023). "In future, we will conduct additional clinical studies and in vivo experiments to further explore the role of TRIM29/KRT5 axis in colon cancer progression." (PMID 37671092, 2023). "In conclusion, our study demonstrated that TRIM29 was upregulated in colon cancer and TRIM29 silencing inhibited colon cancer cell growth." (PMID 37671092, 2023). "TRIM29 knockdown effectively prevented the growth of colon cancer cells, indicating its potential role in colon cancer." (PMID 37671092, 2023). "The present study demonstrated that TRIM29 was upregulated and acted as an oncogene in colon cancer." (PMID 37671092, 2023). "Therefore, they proposed targeting TRIM29-mediated KRT5 ubiquitination levels as a potential new drug target for the treatment of colon cancer." (PMID 39497715, 2024). "Recent studies have reported that TRIM29 plays a significant role in colon cancer progression." (PMID 39497715, 2024). "KRT5 silencing neutralises the inhibitory effects of sh-TRIM29 on colon cancer cell growth." (PMID 37671092, 2023). "Moreover, compared to NCM460 cells, TRIM29 was significantly upregulated in colon cancer cells, especially in SW480 and HCT-116 cells." (PMID 37671092, 2023). "KRT5 knockdown neutralises the inhibitory effect of sh-TRIM29 on colon cancer cell growth and TRIM29 knockdown prevented the proliferation of colon cancer cells by decreasing ubiquitination of KRT5, which enhanced the protein stability and expression of KRT5 in cancer cells." (PMID 37671092, 2023). "In this study, we evaluated the expression of TRIM16, TRIM22, and TRIM29 in colon cancer." (PMID 37671092, 2023). "Therefore, this study aimed to investigate the role of TRIM29 in colon cancer progression." (PMID 37671092, 2023). "However, studies on the role of TRIM29 in colon cancer are limited." (PMID 37671092, 2023). "Thus, targeting TRIM29-mediated ubiquitination levels of KRT5 might be a new direction for colon cancer therapy." (PMID 37671092, 2023). "Five TRIM expression was significantly upregulated (TRIM14, TRIM15, TRIM24, TRIM29, and TRIM31), and the other five TRIM genes showed decreased expression (TRIM1, TRIM3, TRIM9, TRIM22, and TRIM73) in both colon cancer (COAD) and rectal cancer (READ)." (PMID 38769340, 2024).
colon cancer (continued). "However, the association between TRIM29 and KRT5 in colon cancer remains unclear." (PMID 37671092, 2023). "After sh-TRIM29 1# and 2# transfection, the cell viability, colony formation, and number of EDU positive cells significantly declined, suggesting that TRIM29 silencing decreased the proliferation of colon cancer cells." (PMID 37671092, 2023). "No study has reported the role of TRIM29 and KRT in colon cancer." (PMID 37671092, 2023).
melanoma (4 papers, 2010 to 2025). A malignant, usually aggressive tumor composed of atypical, neoplastic melanocytes. "Expression of TRIM7 and TRIM29 was mostly low in metastatic melanoma, as represented in blue in the figure, and mostly high in primary melanoma, represented in red." (PMID 33118318, 2020). "The results showed that compared with normal lines, TRIM27 was highly expressed in melanoma cell line A375, and TRIM29 was downregulated in melanoma cell line A375, and both had statistical significance (p < 0.05)." (PMID 33118318, 2020). "TRIM29 appeared to have low expression in metastatic melanoma and high expression in primary melanoma." (PMID 33118318, 2020). "We used the GEPIA database to investigate the prognostic analysis of TRIM2, TRIM7, TRIM8, TRIM18 (MID1), TRIM19 (PML), TRIM27, and TRIM29 in melanoma." (PMID 33118318, 2020). "In the GEPIA database, TRIM2 and TRIM27 expression were significantly higher, and TRIM7 and TRIM29 expression was significantly downregulated in melanoma; these results were consistent with data from the Oncomine database (all p < 0.05)." (PMID 33118318, 2020). "The gene expression of TRIM2 and TRIM27 was markedly higher, and the expression of TRIM7, TRIM8, and TRIM29 was significantly downregulated in melanoma." (PMID 33118318, 2020). "Interestingly, TRIM29 expression was found to be lower in metastatic melanoma but higher in primary melanoma." (PMID 34988104, 2021). "The status of TRIM29 in melanoma also needs further confirmation." (PMID 34988104, 2021). "The role of TRIM29 in melanoma still needs further experimental verification." (PMID 33118318, 2020). "Differential expression of TRIM2, TRIM7, TRIM8, TRIM18 (MID1), TRIM19 (PML), TRIM27, and TRIM29 may play an important role in the development of melanoma." (PMID 33118318, 2020). "We defined clusters corresponding to melanoma (PMEL, MLANA), immune infiltrates (TRBC2, TRAC, TMSB4X), melanophages (CD74, LYZ), keratinocytes (KRT14, TRIM29), blood vessels (CAVIN1, PECAM), and fibroblast‐enriched areas in the dermis (DCN, COL1A2, FBLN1)." (PMID 39846232, 2025). "TRIM7 and TRIM29 were highly expressed in melanocytes in normal skin tissues but were not detectable in melanoma." (PMID 33118318, 2020). "Studies on TRIM29 and melanoma have not yet been found, which may be a good research direction." (PMID 33118318, 2020).
myocarditis (4 papers, 2024). Myocarditis is a condition that is characterized by inflammation of the heart muscle (myocardium). "Inhibition of TRIM29-PERK signaling pathway can reverse the myocarditis caused by inflammatory cytokines such as IL-6, IL1-β and TNF-α." (PMID 38979420, 2024). "Collectively, these data indicate that cardiomyocyte-specific TRIM29 deficiency is sufficient to protect mice from CVB3-induced myocarditis by promoting cardiac antiviral function, attenuating inflammation, reducing cardiac ER stress and apoptosis, and improving cardiac function in vivo." (PMID 38664417, 2024). "Recent studies have shown that TRIM29-PERK signaling pathway plays an important role in promoting CBV-induced myocarditis." (PMID 38979420, 2024). "To further investigate the mechanisms by which Trim29-/- mice exhibited reduced CVB3-induced myocarditis, we checked type I IFN protein levels in heart homogenates and assessed viral replication in heart, pancreas and spleen tissues by ELISA and plaque-forming assay, respectively." (PMID 38664417, 2024). "However, the role of TRIM29 in cardiovascular diseases, such as myocarditis, has remained elusive." (PMID 38664417, 2024). "We found that both TRIM29 protein and ER stress were dramatically increased in the hearts of mice with cardiotropic virus CVB3-induced myocarditis." (PMID 38664417, 2024).
pancreatic ductal adenocarcinoma (4 papers, 2020 to 2025). An infiltrating adenocarcinoma that arises from the epithelial cells of the pancreas. "For instance, the knockdown of Tripartite Motif Containing 29 (TRIM29) suppresses stem cell-like features in pancreatic ductal adenocarcinomas (PDACs), an effect rescued by extracellular ISG15 via an autocrine mechanism." (PMID 40103488, 2025). "TRIM29 silencing attenuates cancer stem cell-like characteristics of pancreatic ductal adenocarcinomas via regulating ISG15 ubiquitination and degradation." (PMID 37671092, 2023). "TRIM29 is thought to be a molecular marker and oncogene for pancreatic ductal adenocarcinoma." (PMID 34988104, 2021). "The cancer stem cell-like features of pancreatic ductal adenocarcinoma are maintained by the autocrine stimulation of extracellular interferon-stimulated gene 15 (ISG15), which is modulated by TRIM29 via Calpain-3 (CAPN3)-mediated posttranslational degradation." (PMID 34988104, 2021).
papillary thyroid carcinoma (4 papers, 2020 to 2025). "Partly consistent with the two reports, we also found TRIM29 expression is upregulated in papillary thyroid cancer tissues." (PMID 32994394, 2020). "In conclusion, our study reported that TRIM29 inhibited miR-873-5P biogenesis via lncRNA CYTOR sponging premiR-873 to upregulate FN1 and promoted invasion of papillary thyroid cancer cells." (PMID 32994394, 2020). "Similarly, TRIM29 inhibits miR-873 biogenesis by LncRNA CYTOR sponging to upregulate FN1 and promote the progression of papillary thyroid cancer cells." (PMID 34988104, 2021).
adenovirus infection (3 papers, 2017 to 2025). "Conversely, TRIM29 deficiency significantly enhances host resistance to Herpes simplex virus type 1 (HSV-1) and adenovirus infections, indicating that TRIM29 functions as a viral-exploited negative regulator of the cGAS-STING-TBK1-IRF3 axis, diminishing its antiviral capacity." (PMID 40697819, 2025). "In addition, lung tissue from TRIM29-knockout mice revealed less inflammation than that from wild-type (TRIM29 positive) mice following adenovirus infection." (PMID 34624052, 2021). "KO of TRIM29 enhanced production of IFN-β and IFN-α in BMDCs in response to HSV-1 or adenovirus infection twofold to fourfold at 6, 12, or 20 h post infection." (PMID 29038422, 2017). "Similarly, compared with WT cells, Trim29-KO BMDMs produced twofold to fivefold more IFN-β and IFN-α in response to HSV-1 or adenovirus infection than did WT BMDMs at 6, 12, or 20 h post infection." (PMID 29038422, 2017). "Furthermore, Trim29-KO BMDCs and BMDMs produced twofold to threefold more IL-6 and TNF-α in response to HSV-1 or adenovirus infection than did WT BMDCs or BMDMs at 12 or 20 h post infection." (PMID 29038422, 2017).
autoimmune disease (3 papers, 2017 to 2022). A disorder resulting from loss of function or tissue destruction of an organ or multiple organs, arising from humoral or cellular immune responses of the individual to their own tissue constituents. "The identification of TRIM29 as a negative regulator of STING in DNA-sensing will have important implications for the understanding of not only antiviral innate immunity but also the pathogenesis of EBV-induced NPC as well as human autoimmune diseases." (PMID 29038422, 2017). "The authors suggest that TRIM29 acts as a negative regulator of DNA-sensing, which most likely play an important role in EBV-induced cancers and autoimmune diseases." (PMID 34624052, 2021).
ischemic stroke (3 papers, 2024 to 2025). A stroke disorder caused by obstruction of blood flow to the brain, due to thrombotic (local blood clot formation) or embolic (due to a blood clot or other material traveling from another site) event. "TRIM29 is an upstream regulatory factor of PERK and can alleviate brain damage caused by ischemic stroke." (PMID 41377071, 2025). "Besides, TRIM29 interacts with NLRC4 inflammasome and attenuates apoptosis and pyroptosis of neurons and microglia cells in ischemic stroke." (PMID 40717974, 2025).
osteosarcoma (3 papers, 2017 to 2021). A usually aggressive malignant bone-forming mesenchymal neoplasm, predominantly affecting adolescents and young adults. "In osteosarcoma and ovarian cancer, TRIM29 induces EMT and chemoresistance, respectively." (PMID 34988104, 2021). "Among them are TRIM2 (up-regulated in osteosarcoma, down-regulated in kidney cancer), TRIM29 (up-regulated in lung cancer and osteosarcoma, down-regulated in liver and prostate cancers), TRIM33 (up-regulated in breast cancer, down-regulated in liver and kidney cancers)." (PMID 33673719, 2021).
squamous carcinoma (3 papers, 2010 to 2022). "In addition to effects of PKCs on the expression of the gene, PKCs can phosphorylate the TRIM29 protein: PMA increases TRIM29 phosphorylation in human squamous carcinoma cells." (PMID 20454669, 2010).
bladder tumor (2 papers, 2020 to 2026). "In this study, we find that Trim29 expression in K5+ basal cells is linked to the inflammatory response and is critical for bladder tumor formation and invasive progression." (PMID 42239777, 2026). "Furthermore, our immunohistochemical data is in good agreement with previous reports that demonstrate high levels of TFAP2A, P63, and TRIM29 within basal bladder tumors that have areas of squamous differentiation." (PMID 32822399, 2020).
cardiomyopathy (2 papers, 2024 to 2025). A disease of the heart muscle or myocardium proper. "Parallel findings human subjects indicated heightened TRIM29 and ER stress levels in patients with cardiomyopathy relative to healthy normal controls, as indicated by the TRIM29 and ER stress marker KDEL." (PMID 38664417, 2024). "Therefore, TRIM29, TRIM18, and PARP9 may regulate ferroptosis to manage cardiomyopathy." (PMID 40356926, 2025).
liver cancer (2 papers, 2021). An epithelial or non-epithelial malignant neoplasm that arises from the liver. "Moreover, the results of the present study showed that HOXA3 might interact with TRIM29, ENO1 and SFN, which was reportedly associated with the occurrence of liver cancer." (PMID 33683826, 2021).
lung adenocarcinoma (2 papers, 2020 to 2022). A carcinoma that arises from the lung and is characterized by the presence of malignant glandular epithelial cells. "Recently, it has been reported that PHGDH and TRIM29 are expressed in lung adenocarcinoma, and are indicators of poor prognosis." (PMID 35204409, 2022).
metastatic melanoma (2 papers, 2020 to 2024). A melanoma that has spread from its primary site to another anatomic site. "Additionally, TRIM29 is also reduced in metastatic melanoma." (PMID 39766071, 2024).
pancreatic adenocarcinoma (2 papers, 2016 to 2025). "In pancreatic adenocarcinoma cells, phosphorylated TRIM29 at Ser550 by MAPKAP kinase 2 induces radioresistance of cancer cells." (PMID 27081037, 2016).
Sepsis (2 papers, 2021 to 2025). Sepsis is defined as life-threatening organ dysfunction caused by a dysregulated host response to infection. "Another mechanism has been demonstrated that the E3 ubiquitin ligase TRIM29 regulated the activation of alveolar macrophages and had a critical role in the protection against LPS-induced sepsis by Haemophilus influenzae." (PMID 34804016, 2021).
Stroke (2 papers, 2023 to 2025). Sudden impairment of blood flow to a part of the brain due to occlusion or rupture of an artery to the brain. "Therefore, TRIM29 may control stroke by regulating PERK-mediated protein lactylation." (PMID 41377071, 2025).
asthma (1 paper, 2024). "Given the important roles of AECs and respiratory viral infection in asthma development and exacerbation, TRIM29 and DHX15 modulators may mitigate asthma by influencing AEC pyroptosis and immune response during viral infection." (PMID 39611173, 2024).
Barrett esophagus (1 paper, 2023). Esophageal lesion lined with columnar metaplastic epithelium which is flat or villiform. "The results showed that TRIM29 expression in precancerous lesions of ESCA, including Barrett’s esophagus (BE) and dysplasia, was significantly lower than in matched adjacent/normal esophageal epithelial tissues." (PMID 37365152, 2023).
chronic pancreatitis (1 paper, 2020). A chronic inflammatory process causing damage and fibrosis of the pancreatic parenchyma. "In adenocarcinoma cells, the expression level of TRIM29 is more than 20 times higher than that of normal pancreatic and chronic pancreatitis cells, which suggests that TRIM29 is a good biomarker." (PMID 32640423, 2020).
colitis (1 paper, 2026). Inflammation of the colon. "Third, the upstream regulators and downstream pathways mediating TRIM29’s role in colitis were largely inferred from transcriptomic data and require direct experimental validation to elucidate the precise molecular mechanisms involved." (PMID 41601651, 2026).
COVID-19 (1 paper, 2022). A disease caused by infection with severe acute respiratory syndrome coronavirus 2. "Interestingly, PVRL1 and TRIM29 are both close to the sex-biased COVID-19 association SNP rs140657166, and TRIM29 is adjacent to rs2443615, with the two SNPs 115.5-Mbp far away from each other." (PMID 36353114, 2022). "Taken together, all pieces of evidence strongly support the involvement of PVRL1, TRIM29, and TRIM21 in COVID-19, but further investigation is warranted." (PMID 36353114, 2022).
cutaneous melanoma (1 paper, 2021). A primary melanoma arising from atypical melanocytes in the skin. "But the function of TRIM29 in cutaneous melanoma remained still unknown." (PMID 33842346, 2021).
diabetes (1 paper, 2024). "Given the importance of PERK in the pathogenesis of cancer, diabetes, and neurodegenerative diseases, the TRIM29-PERK axis may be therapeutically targeted to treat those diseases." (PMID 38664417, 2024). "Given PERK’s involvement in the onset of diseases like cancer, diabetes, and neurodegenerative disorders, it’s tempting to postulate that the TRIM29-mediated SUMOylation of PERK might be a key regulator in their respective pathogenesis." (PMID 38664417, 2024).
diabetic nephropathy (1 paper, 2024). "Alterations in SERPINB5 expression have been observed in UC epithelial cells, while TRIM29 has been demonstrated in promoting pyroptosis of diabetic nephropathy podiocytes through the NF-kB/NLRP3 inflammasome pathway." (PMID 38426148, 2024).
endometrial cancer (1 paper, 2017). Primary or metastatic malignant neoplasm involving the endometrium (mucous membrane that lines the endometrial cavity). "Microarray analysis indicates that TRIM29 is overexpressed in the lung, pancreatic, gastric, bladder, colorectal, ovarian, and endometrial cancers, as well as plasma cell myeloma." (PMID 29038422, 2017).